FKBP5 (FKBP prolyl isomerase 5)
Diseases named in the same sentence as FKBP5 in open-access papers (continued):
Sharing a sentence is not in itself a finding about the gene and the disease.
neurodegenerative disease (4 papers, 2022 to 2024). A disorder of the central nervous system characterized by gradual and progressive loss of neural tissue and neurologic function. "Decreased expression of pro-inflammatory genes, which are associated with neurodegenerative disease or astrocyte and microglia phenotypes Cd40, C1qB, Cd68, Cd45, Aqp-4, Il1α, Fkbp5, Ggta1, Cd16, H2-T23, and Serping1, was observed following C-32:6 treatment and C1qC, Tspo, and Gbp2 with FFA C-34:6." (PMID 37740008, 2023). "It is worth mentioning that while we have focused on AD as an illustrative example, it may be plausible that SKA2, FKBP5, and the SA pathway may also play roles in other neurodegenerative diseases." (PMID 38528004, 2024).
endocrine disorders (1 paper, 2022). "FKBP5 is associated with endocrine disorders, which are highly consistent with the symptoms of PCOS." (PMID 35787810, 2022).
immune dysfunction (1 paper, 2024). "Specific PROTACs targeting GR or FKBP5 may cause systemic side effects such as immune dysfunction or disrupted stress hormone regulation, highlighting the need for improved specificity and reduced toxicity in PROTAC design for stress-related disorders." (PMID 39361217, 2024).
neoplastic disorders (1 paper, 2026). "Despite extensive research on FKBP5 in individual disease contexts, a critical gap remains in understanding how its DNAm serves as a unifying epigenetic mechanism across psychiatric, metabolic, and neoplastic disorders." (PMID 41664704, 2026).
FKBP5 also shares sentences with these, for which no sentence is quoted: colorectal cancer (5 papers); glucocorticoid resistance (5); gastric cancer (4); myeloma (3); acute lymphoblastic leukemia (2); acute myocardial infarction (2); adenocarcinoma (2); cannabis abuse (2); dementia (2); hyperlipidaemia (2); neurological disorders (2); non-small cell lung carcinoma (2); -traumatic stress disorder (1); acute coronary syndrome (1); acute respiratory distress syndrome (1); Adrenal insufficiency (1); age (1); agoraphobia (1); Alcohol (1); amyotrophic lateral sclerosis (1); antiphospholipid syndrome (1); atherosclerosis (1); autism spectrum disorder (1); autoimmune Addison’s disease (1); autoimmune disease (1); brain cancer (1); brain diseases (1); bruxism (1); cardiac hypertrophy (1); childhood-onset schizophrenia (1).
A further 46 diseases each share a sentence with FKBP5 in 1 paper.